EMC8 (ER membrane protein complex subunit 8)
Description:
Part of the endoplasmic reticulum membrane protein complex (EMC) that enables the energy-independent insertion into endoplasmic reticulum membranes of newly synthesized membrane proteins. Preferentially accommodates proteins with transmembrane domains that are weakly hydrophobic or contain destabilizing features such as charged and aromatic residues. Involved in the cotranslational insertion of multi-pass membrane proteins in which stop-transfer membrane-anchor sequences become ER membrane spanning helices. It is also required for the post-translational insertion of tail-anchored/TA proteins in endoplasmic reticulum membranes. By mediating the proper cotranslational insertion of N-terminal transmembrane domains in an N-exo topology, with translocated N-terminus in the lumen of the ER, controls the topology of multi-pass membrane proteins like the G protein-coupled receptors. By regulating the insertion of various proteins in membranes, it is indirectly involved in many cellular processes (Probable).
Synonyms: C16orf2; C16orf4; COX4NB; FAM158B; NOC4
Tractability: Small molecule: a structure with a bound ligand is known. Antibody: UniProt places it where antibodies can reach, with high confidence. PROTAC: ubiquitination databases record sites on it; its protein half-life has been measured.
Gene: Protein-coding gene on chromosome 16 (85,771,758 to 85,799,625, reverse strand). Ensembl gene ENSG00000131148.
Subcellular location: Endoplasmic reticulum membrane
Subcellular location (Human Protein Atlas): Endoplasmic reticulum; Golgi apparatus
Gene Ontology:
Molecular function: membrane insertase activity; protein binding
Biological process: protein insertion into ER membrane by stop-transfer membrane-anchor sequence; tail-anchored membrane protein insertion into ER membrane
Cellular component: cytoplasm; EMC complex; endoplasmic reticulum; endoplasmic reticulum membrane; membrane
Genetic constraint (gnomAD): Loss-of-function variants: 10 observed, 18.55 expected, observed/expected ratio (o/e) 0.54, 90% interval 0.33 to 0.92. The synonymous counts are far from expectation, so gnomAD's model fits this gene poorly and the ratio says little. Missense variants: 233 observed, 240.91 expected, observed/expected ratio (o/e) 0.97, 90% interval 0.87 to 1.08. Synonymous variants: 128 observed, 99.23 expected, observed/expected ratio (o/e) 1.29, 90% interval 1.12 to 1.49.
Homologues: Orthologues: chimpanzee EMC8 (100% identical), macaque EMC8 (100% identical), dog EMC8 (99% identical), guinea pig EMC8 (95% identical), mouse Emc8 (92% identical), rat Emc8 (92% identical), tropical clawed frog emc8 (73% identical), zebrafish emc8 (68% identical), Drosophila melanogaster EMC8-9 (37% identical), Caenorhabditis elegans F25H2.4 (26% identical). Paralogues in human: EMC9 (43% identical).
Diseases named in the same sentence as EMC8 in open-access papers:
EMC8 is named in the same sentence as 6 diseases in open-access papers, as found by Europe PMC text mining. Sharing a sentence is not in itself a finding about the gene and the disease. The quoted sentences say what the papers report.
breast carcinoma (2 papers, 2011 to 2017). "Upon inhibition of miR-7641 expression, the expressions of several of the target genes (RPS16, RNF4, EMC8, and MSRB3) increased, CUL3 expression decreased, and other genes, including PIGC, remained unchanged in MCF-7 breast cancer cells." (PMID 28827731, 2017).
autoimmune disease (1 paper, 2017). A disorder resulting from loss of function or tissue destruction of an organ or multiple organs, arising from humoral or cellular immune responses of the individual to their own tissue constituents. "EMC8 and COX4I1 RNA expression was relatively unchanged by activation, whereas IRF8 expression was upregulated 97-fold, coincident with the induction of 16 intergenic IRF8 PIRs, four of which overlap autoimmune disease fine-mapped variants." (PMID 28870212, 2017).
encephalitis (1 paper, 2025). An acute inflammatory process affecting the brain parenchyma. "The resultsindicated that in the encephalitis group, potassium channel-related gene KCNN3,cell development-related genes EMC8, DANCR, and ASPN, along with thetranscription factor ZNF296, were significantly upregulated." (PMID 40985687, 2025).
melanoma (1 paper, 2022). A malignant, usually aggressive tumor composed of atypical, neoplastic melanocytes. "The most significant differences in melanoma are NOMO1, PIGT, VKORC1, PDIA5 and DDX11, and the most significant differences in uterine cancer are CTU2, EMC8, TUBG1, CLPP and LONP1." (PMID 34951103, 2022).
cancer (2 papers, 2017 to 2022). A tumor composed of atypical neoplastic, often pleomorphic cells that invade other tissues. "The data showed that inhibition of miR-7641 upregulated RPS16 in all cancer cell lines, while TNFSF10, RNF4, EMC8 and CUL3 responded irregularly." (PMID 28827731, 2017).
EMC8 also shares sentences with these, for which no sentence is quoted: uterine cancer (1 paper).